KLF10 (KLF transcription factor 10)
Diseases named in the same sentence as KLF10 in open-access papers (continued):
Sharing a sentence is not in itself a finding about the gene and the disease.
steatosis (5 papers, 2014 to 2021). Increased lipid within the cytoplasm of cells. "Compared with control cells, KLF10-transfected HepG2 cells showed significant less recovered oil red O content (determined by MOD) suggested that overexpression of KLF10 rescued steatosis in liver cells." (PMID 34869587, 2021). "In the present study, we demonstrated that liver damage, such as lipid accumulation and steatosis, was aggravated in KLF10-knockout mice." (PMID 34869587, 2021). "We therefore hypothesize a scenario in which sugar-induced steatosis is attenuated by KLF10, which acts both upstream of ChREBP—through repression of glucose uptake and downstream of ChREBP—via the repression of de novo lipogenesis." (PMID 34402428, 2021). "Although it is observed that high fat diet induced steatosis is accompanied by depletion of hepatic regulatory T cells, association of this regulatory T cell depletion and KLF10 has never been investigated." (PMID 24986741, 2014). "Wild type and Klf10-/- mice were fed with MCDD for 4 weeks and livers were sampled at two different ZTs during the rest phase as the steatosis and inflammatory foci are more important during this time window of the 24-h cycle (ZT3 and ZT9)." (PMID 32699233, 2020).
melanoma (4 papers, 2017 to 2024). A malignant, usually aggressive tumor composed of atypical, neoplastic melanocytes. "Pathway analysis of the microarray data using genes whose expression was significantly decreased by at least 1.5 fold indicated that KLF10 participates in several processes including the melanoma pathway and metabolism of xenobiotics by cytochrome P450 among others." (PMID 29930344, 2018). "Among them, KLF4 and KLF10 where those TFs that best correlate with miR-182 in melanoma cell lines." (PMID 28412746, 2017).
nonalcoholic steatohepatitis (4 papers, 2014 to 2025). "In C57BL/6 mice, the mRNA and protein expression level of KLF10 was significantly increased in diet-induced non-alcoholic steatohepatitis and collagen producing activated hepatic stellate cells." (PMID 32256445, 2020). "KLF10 expression was significantly increased in diet-induced nonalcoholic steatohepatitis (NASH) and collagen-producing activated hepatic stellate cells." (PMID 29799499, 2018).
oral squamous cell carcinoma (4 papers, 2020 to 2023). "In oral squamous cell carcinoma, KLF10 was identified as a differentially expressed circadian-related gene that was correlated with OS (p < 0.05) and the drug response (p = 0.0014)." (PMID 37958386, 2023). "By directly binding to the LINC00629 promoter to induce Mcl1 degradation, KLF10 exerts antitumor activity in oral squamous cell carcinoma treated with apigenin, a flavonoid." (PMID 37958386, 2023).
osteosarcoma (4 papers, 2014 to 2024). A usually aggressive malignant bone-forming mesenchymal neoplasm, predominantly affecting adolescents and young adults. "KLF10 has been shown to have an impact on the proliferation of osteoblasts, osteoclasts and osteosarcoma cells, which could be the cause for the observed reduced proliferation rate." (PMID 24885297, 2014). "The function of HES1 and KLF10 in bone biology also implies a function for these genes in osteosarcoma development." (PMID 24885297, 2014). "Moreover, MSCs‐EVs were found to deliver noncoding RNA activated by DNA damage to osteosarcoma cells, promoting the proliferation and migration capabilities of osteosarcoma cells via modulation of the miR‐30c‐5p/KLF10 signaling axis." (PMID 39070181, 2024). "We believe that LSAMP is a tumor suppressor gene in osteosarcomas and that LSAMP suppress tumors by reducing the proliferation rate of cancer cells, possibly through upregulation of one or more of the genes HES1, CTAG2 and KLF10." (PMID 24885297, 2014).
ovarian carcinoma (4 papers, 2012 to 2025). A malignant neoplasm originating from the surface ovarian epithelium. "In ovarian cancer, transcription factor KLF10 activated by circadian rhythm gene expression serves as a risk factor for epithelial ovarian cancer, histopathologic subtype, and invasiveness." (PMID 29799499, 2018). "The goal of the current study was to examine single nucleotide polymorphisms (SNPs) in circadian genes BMAL1, CRY2, CSNK1E, NPAS2, PER3, REV1 and TIMELESS and downstream transcription factors KLF10 and SENP3 as predictors of risk of epithelial ovarian cancer (EOC) and histopathologic subtypes." (PMID 26807442, 2015).
atherosclerosis (3 papers, 2014 to 2024). A disease characterized by the build-up of fatty material and calcium deposition in the arterial wall resulting in partial or complete occlusion of the arterial lumen. "Although KLF10 deficient mice are reported to grow and reproduce normally, these mice demonstrate defects in healing potential, and abnormally enhanced T cell function resulting in aggravated atherosclerosis." (PMID 24986741, 2014). "Next, the effects of KLF10 on Tregs-regulated macrophages in atherosclerosis and the effects of MSCs, IL-12p35, HCW9302, MicroRNA-33, STAT4, and HHcy on Tregs and macrophages in atherosclerosis are explained." (PMID 39582868, 2024). "highlighted the important role of KLF10 in mediating Treg-macrophage coupling in atherosclerosis." (PMID 39582868, 2024). "Transfer of KLF10-deficient T-cells failed to suppress the development of atherosclerosis in apolipoprotein E knockout mice with high-fat diet." (PMID 27899146, 2016). "Krüppel-like factor 10 (KLF10) is a transcription factor in CD4+ T cells, which can regulate the progression of atherosclerosis." (PMID 39582868, 2024).
colon cancer (3 papers, 2013 to 2022). "Treatment of colon cancer cells with 15-hydroxy-eicosatetraenoic acid (15S-HETE), an endogenous ligand for PPARγ, arrests the growth of colon cancer cells via a PPARγ dependent pathway involving increased expression of KLF10 and decreased Bcl-2 (B cell lymphoma 2) expressions." (PMID 29799499, 2018).
diabetic nephropathy (3 papers, 2019 to 2024). "A recent study has demonstrated the involvement of KLF10 in renal fibrosis, specifically diabetic nephropathy." (PMID 38279278, 2024). "Consistent with the notion, we also show that levels of both KDM6A and KLF10 proteins or mRNAs are substantially elevated in kidney tissues or in urinary exosomes of human diabetic nephropathy patients as compared with control subjects." (PMID 30948420, 2019). "Therefore, KLF10 plays a distinct role in promoting DN, making it a promising therapeutic target for diagnosing diabetic nephropathy." (PMID 38279278, 2024). "Moreover, to further confirm our study findings, we attempted to examine levels of KDM6A, KLF10, and nephrin mRNAs in urinary exosomes of control subjects and patients with diabetic nephropathy (n = 12 for each group)." (PMID 30948420, 2019). "Quantitative analysis of mRNA contents in human urinary exosomes also showed that higher levels of exosomal KDM6A and KLF10 mRNAs, accompanied by lower levels of nephrin mRNA, were significantly observed in diabetic nephropathy subjects than in control subjects." (PMID 30948420, 2019). "Importantly, both KLF10 and KDM6A mRNA and protein levels increased in kidney tissues of patients with diabetic nephropathy." (PMID 38279278, 2024).
esophageal squamous cell carcinoma (3 papers, 2017 to 2022). Esophageal squamous cell carcinoma (ESCC) is a type of esophageal carcinoma (EC) that can affect any part of the esophagus, but is usually located in the upper or middle third. "Kruppel-like factor 10 (KLF10) is a DNA-binding transcriptional regulator that acts as a tumor suppressor by regulating the transcription level of target genes in multiple cancers, including PC and esophageal squamous cell carcinoma." (PMID 34635142, 2021).
glioma (3 papers, 2021 to 2023). A benign or malignant brain and spinal cord tumor that arises from glial cells (astrocytes, oligodendrocytes, ependymal cells). "In the intricate landscape of glioma pathogenesis, the elucidation of risk scores derived from pivotal hub genes—RPL3, RPL12, PTEN, IFNGR2, KLF10, PLAUR, MSN, and IKBIP—emerged as a critical component in understanding the disease’s progression and patient stratification." (PMID 38137116, 2023). "This does not mean that DRP2, IGFBP5, KLF10, ARHGAP11A and NRP2 are not essential genes for glioma pathogenesis, given the missing data and limited sample size we found." (PMID 34434651, 2021). "Among them, ARHGAP11A, DRP2, HNRNPA3, KLF10, PAIP1, and RCN1 have not yet been studied in gliomas." (PMID 34434651, 2021).
keloid (3 papers, 2020 to 2024). An irregularly shaped, elevated mark on the skin caused by deposits of excessive amounts of collagen during wound healing. "KLF10 knockdown decreased collagen content, proliferation, and migration of keloid fibroblasts." (PMID 38279278, 2024). "Knockout of KLF10 represses type I and III collagen, fibronectin, and matrix metalloproteinase 9 and inhibits the migration of keloid fibroblast cells." (PMID 35565995, 2022).
leukemia (3 papers, 2012 to 2021). A malignant (clonal) hematologic disorder, involving hematopoietic stem cells and characterized by the presence of primitive or atypical myeloid or lymphoid cells in the bone marrow and the blood. "KLF10 enhances human leukemia cell death by upregulating Bim and Bax pro-apoptotic proteins." (PMID 34805140, 2021).
oral cancer (3 papers, 2020 to 2023). "The univariate analysis indicated that an early stage (I) of oral cancer and a high expression of KLF10 were significantly associated with a better prognosis (p = 0.047 and p = 0.043, respectively)." (PMID 33379261, 2020). "Our study aimed more to directly identify the prognostic value of the biomarker and succeeded in demonstrating that a high KLF10 expression is associated with a more favorable clinical outcome in oral cancer." (PMID 33379261, 2020). "KLF10 is a gene involved in a variety of signaling pathways and has been described as a potential prognostic marker in patients with oral cancer in early stages." (PMID 34830760, 2021). "The significant character of KLF10 in predicting the clinical outcome of oral cancer was discovered." (PMID 33379261, 2020). "In our study, we enrolled 286 patients with oral cancer and analyzed the histological expression of KLF10 in specimens removed from the patients." (PMID 33379261, 2020). "Materials and Methods: KLF10 immunoreactivity was analyzed by immunohistochemical (IHC) stain analysis in 286 cancer specimens from primary oral cancer patients." (PMID 33379261, 2020). "We studied the impact of KLF10 expression on the clinical outcomes of oral cancer patients to identify its role as a prognostic factor in oral cancer." (PMID 33379261, 2020). "The remarkable role of KLF10 in mediating carcinogenesis has aroused interest in predicting the clinical outcome of oral cancer." (PMID 33379261, 2020). "In the present study, KLF10 levels were measured by the immunohistochemical (IHC) stain analysis of oral cancer specimens." (PMID 33379261, 2020). "The present study, a novel model researching the relationship between high KLF10 expression and oral cancer prognosis, reproduced the scoring system to clearly address the clinical association." (PMID 33379261, 2020). "Moreover, KLF10 expression can also serve as an independent prognostic marker in oral cancer patients, especially those in early-stage." (PMID 36755291, 2023). "KLF10 expression could potentially be used as an independent prognostic marker in patients with oral cancer, especially those at the early T and N stages." (PMID 33379261, 2020). "KLF10 may also act as a protective factor against oral cancer." (PMID 33379261, 2020).
Osteopenia (3 papers, 2016 to 2023). Osteopenia is a term to define bone density that is not normal but also not as low as osteoporosis. "It is speculated that APOA1, FBN1, NOTCH1, SYT7 and KLF10 played key roles in regulating bone metabolic balance and in reversible osteopenia after PAOO, which might be involved in the accelerated tooth movement." (PMID 38012627, 2023). "It is speculated that APOA1, FBN1, NOTCH1, SYT7 and KLF10 play key roles in regulating bone metabolic balance and in reversible osteopenia after PAOO, which might be involved in the accelerated tooth movement." (PMID 38012627, 2023). "KLF10 knock-out (KO) mice have slow osteoblast production of RANKL (receptor activator of nuclear factor kappa-B ligand) and high levels of osteoprotegerin (OPG), which delays OCL differentiation, leading to a reduced bone turnover and a loss of bone (osteopenia)." (PMID 29799499, 2018).
pancreatic adenocarcinoma (3 papers, 2020 to 2023). "In a murine model of spontaneous pancreatic adenocarcinoma (PDAC), additional KLF10 depletion accelerated distant metastasis." (PMID 34702956, 2021).
renal cell carcinoma (3 papers, 2016 to 2020). "Stimulation of the TGF-β1 promoter by KLF10 in HAEo(−) and 293 cells suggests that KLF10 is a VHL target that regulates the TGF-β1 promoter in renal cell carcinoma." (PMID 29799499, 2018).
renal fibrosis (3 papers, 2019 to 2024). A final common manifestation of a wide variety of chronic kidney diseases characterized by glomerulosclerosis and tubulointerstitial fibrosis. "In conclusion, KLF10 mediated DKK-1 expression played a pivotal role in high-glucose-induced renal fibrosis." (PMID 35565995, 2022). "In the future, the development of specific small interference RNA for knockout of KLF10 may be a promising clinical therapy for renal fibrosis." (PMID 35565995, 2022). "Moreover, knockout of KLF10 reduced the renal fibrosis, as shown by Masson’s Trichrome analysis." (PMID 35565995, 2022). "Although the specific role of KLF10 in renal fibrosis was not explored in this study, their findings suggest its potential involvement in TGF-β signaling modulation and renal fibrosis development." (PMID 38279278, 2024).
type 2 diabetes (3 papers, 2016 to 2022). "Genetic variants of KLF10 are associated with susceptibility to type 2 diabetes." (PMID 27899146, 2016).
acute kidney injury (2 papers, 2023). Sudden and sustained deterioration of the kidney function characterized by decreased glomerular filtration rate, increased serum creatinine or oliguria. "Noteworthy is that transcription factor ZBTB7A positively regulated the proliferative inhibiting impact of KLF10 in acute kidney injury (AKI)." (PMID 37107656, 2023). "Our findings suggest that downregulation of KLF10 positively contributed to tubular regeneration in cisplatin induced acute kidney injury via ZBTB7A-KLF10-PTEN axis, which gives insight into the novel therapeutic and diagnostical target of AKI." (PMID 36878898, 2023). "Collectively, our study proposed a novel mechanism wherein downregulation of KLF10 contributed to the proliferation of survived renal tubular cells in cisplatin-induced acute kidney injury via ZBTB7A-KLF10-PTEN axis, which might be a promising diagnostic and therapeutic target of AKI." (PMID 36878898, 2023).
brain tumors (2 papers, 2018 to 2022). "Gene expression profiling analysis indicated that KLF10 expression is low in metastatic brain tumors." (PMID 35743973, 2022).
breast tumor (2 papers, 2015 to 2018). "KLF10 expression is reduced in breast tumors relative to normal tissue and is inversely correlated with stage of disease." (PMID 26807442, 2015).
cervical cancer (2 papers, 2018 to 2023). A primary or metastatic malignant neoplasm involving the cervix. "To explore this further, we knocked down KLF10 in the SiHa cervical cancer cell line and perform microarray analyses." (PMID 29930344, 2018).
dyslipidemia (2 papers, 2016 to 2021). "Present data provides a possibility that visceral fat adiposity-associated reduction in peripheral blood KLF10 mRNA level is related to the pathogenesis of the metabolic syndrome, although further clinical studies would be needed in future." (PMID 27899146, 2016). "Impairment of KLF10 function is associated with lipid accumulation and alterations of glucose metabolism, suggesting that activation of the AMPK-KLF10 axis could be a potential therapeutic target for the treatment of metabolic syndrome, including NAFLD." (PMID 34869587, 2021).
esophageal cancer (2 papers, 2017 to 2023). A primary or metastatic malignant neoplasm involving the esophagus. "Higher miR-340-5p expression and lower KLF10 expression in plasma exosomes from patients with esophageal cancer patients were associated with poorer radiation responses and prognosis." (PMID 37958386, 2023). "Metformin might decrease radioresistance in pancreatic and esophageal cancers by elevating KLF10 expression." (PMID 37958386, 2023). "Five nucleoproteins MISP, KLF10, KLF15, PPP1R18, and RXRβ were identified by oligonucleotide trapping, as the binding factors on the TRE under TPA stimulation, and were expressed at varying expression levels in esophageal cancer." (PMID 29098164, 2017). "Several nucleoproteins (MISP, KLF10, KLF15, PPP1R18, and RXRβ) have been identified by affinity chromatography and mass spectrometry and could respond to TPA stimulation and regulate LCN2 expression in esophageal cancer cells." (PMID 29098164, 2017).
gastric cancer (2 papers, 2022 to 2024). A primary or metastatic malignant neoplasm involving the stomach. "Although KLF10 is associated with several cancers, its role in gastric cancer remains to be elucidated." (PMID 35743973, 2022). "Univariate analysis revealed that in patients with gastric cancer, advanced stages and low KLF10 levels were associated with survival." (PMID 35743973, 2022). "Moreover, in the gastric cancer line, KLF10 overexpression altered the Bcl-2/Bax ratio, caused caspase-3 activation, and finally, caused apoptosis." (PMID 35743973, 2022). "KLF10 was also an independent prognostic factor of gastric cancer, especially the intestinal type of gastric cancer." (PMID 35743973, 2022). "Since the pathogenesis of gastric cancer involves several steps and several factors/co-factors, future studies should focalize on the relationship between KLF10 expression and some of these factors, for example, Helicobacter pylori infection." (PMID 35743973, 2022). "After adjusting for age, gender, and stage, KLF10 expression was also found to be an independent prognostic factor in the survival of patients with gastric cancer." (PMID 35743973, 2022). "After adjusting for gender, age, and stage, KLF10 expression was found to be an independent prognostic factor of intestinal gastric cancer." (PMID 35743973, 2022). "Multivariate analysis indicated that age, gender, advanced stages, and KLF10 expression were independent prognostic factors of the survival of patients with gastric cancer." (PMID 35743973, 2022). "We performed IHC staining by using gastric cancer TMAs to evaluate the relationship between the expression level of KLF10 and the clinical parameters of gastric cancer." (PMID 35743973, 2022). "In this study, KLF10 expression was significantly higher in intestinal-type gastric cancer than in other types." (PMID 35743973, 2022). "Materials and Methods: In this study, we performed immunohistochemical staining for KLF10 expression in 121 gastric cancer sections." (PMID 35743973, 2022). "Our results collectively revealed that KLF10 may be involved in the carcinogenesis of gastric cancer, especially intestinal-type gastric cancer." (PMID 35743973, 2022). "In addition, KLF10 was an independent factor in the overall survival of patients with gastric cancers." (PMID 35743973, 2022). "Univariate and multivariate analyses also revealed that KLF10 could be a prognostic factor of gastric cancer." (PMID 35743973, 2022). "Our findings provided evidence that KLF10 may function as a tumor suppressor gene in gastric cancer." (PMID 35743973, 2022). "Furthermore, KLF10 expression was low in the diffuse type of gastric cancer." (PMID 35743973, 2022). "Our findings collectively suggested that KLF10 may be a tumor suppressor in gastric cancer." (PMID 35743973, 2022). "However, the role of KLF10 in gastric cancer formation remains unclear." (PMID 35743973, 2022).